SHH (sonic hedgehog signaling molecule)
Diseases named in the same sentence as SHH in open-access papers (continued):
Sharing a sentence is not in itself a finding about the gene and the disease.
endometriosis (2 papers, 2020 to 2022). The growth of functional endometrial tissue in anatomic sites outside the uterine body. "Our previous publication found that the Sonic Hedgehog (SHH) signaling pathway was activated in endometriosis." (PMID 35933378, 2022). "Our study suggested that inhibition of the SHH pathway is involved in cell proliferation and invasive growth in the pathogenesis of endometriosis." (PMID 35933378, 2022). "Our purpose was to demonstrate the role of the SHH pathway in the proliferation, migration and invasion of endometrial stromal cells (ESCs) from eutopic endometrium derived from patients with endometriosis." (PMID 35933378, 2022). "The present research further extended the mechanistic study of the SHH signaling pathway in endometriosis." (PMID 35933378, 2022). "In our previous study, we investigated the effect of the SHH signaling pathway on the development of endometriosis." (PMID 35933378, 2022). "Our previous research indicated that the SHH pathway was upregulated in eutopic endometrial tissues of endometriosis." (PMID 35933378, 2022). "In this study, we used the GLI inhibitor GANT61 to inhibit the SHH pathway and explored the effect of this pathway on the pathogenesis of endometriosis." (PMID 35933378, 2022). "The occurrence of lesions, indicative of endometriosis, was 100% in the isotype control treated group and 80% in anti-SHH treated group (p = 0.08)." (PMID 32977859, 2020). "In addition, using an in vitro assay, we found that blockade of the SHH signaling pathway can significantly reduce cell proliferation and that the SHH pathway is essential for cell proliferation in endometriosis." (PMID 35933378, 2022). "Thus, we believe that blockade of the targeted factor of the SHH signaling pathway will decrease the expression and activation of the pathway and will also inhibit the development of endometriosis." (PMID 35933378, 2022). "Barricading the SHH signaling pathway, the expression of the cell proliferation-related protein Ki67 in the experimental group showed a stronger decrease than that in the control group in the animal model of endometriosis." (PMID 35933378, 2022). "To examine the effect of inhibiting the SHH signaling pathway on endometriosis, we first isolated ESCs from eutopic endometrial tissues of patients with or without endometriosis and identified the extracted cells by morphological observation and immunofluorescence." (PMID 35933378, 2022). "This study tested whether SHH signaling in endometrial stromal cells (ESCs) was critical for the pathogenesis of endometriosis." (PMID 35933378, 2022). "Consequently, we assessed regulation of the SHH signaling pathway with the development of endometriosis." (PMID 35933378, 2022). "Nevertheless, little is known about whether activation of the SHH pathway promotes the occurrence and development of endometriosis." (PMID 35933378, 2022). "Therefore, the SHH signaling pathway may serve as a novel target for endometriosis therapy in the future." (PMID 35933378, 2022). "However, the role of the SHH signaling pathway in endometriosis still needs to be elucidated." (PMID 35933378, 2022). "Therefore, we further investigated the mechanism of the SHH pathway in endometriosis." (PMID 35933378, 2022). "Sonic hedgehog (SHH) and its downstream signalling transcription factor GLI1 are upregulated in the eutopic endometrium of women with endometriosis in comparison to healthy controls." (PMID 32977859, 2020). "SHH, SMO, GLI1 and GLI3 expression was strongly increased with clinical stages in the eutopic endometrium, which suggested that the SHH signaling pathway was abnormally activated in endometriosis." (PMID 35933378, 2022). "Very weak to no signal was detected in isotype and anti-SHH lesions from the endometriosis model (representative of 3 animals)." (PMID 32977859, 2020).
esophageal adenocarcinoma (2 papers, 2019 to 2022). A malignant tumor with glandular differentiation arising predominantly from Barrett mucosa in the lower third of the esophagus. "Abnormalities within the Sonic Hedgehog (SHH), Bone Morphogenetic Protein (BMP) and SMAD4 signalling pathways have been associated with the malignant behavior of esophageal adenocarcinoma (EAC)." (PMID 35902550, 2022). "Taken together, our findings identify KLF5 as a potential oncogene in esophageal adenocarcinoma and suggest a novel connection between KLF5 and the SHH pathway." (PMID 31401336, 2019).
Ewing sarcoma (2 papers, 2020 to 2022). A small round cell tumor that lacks morphologic, immunohistochemical, and electron microscopic evidence of neuroectodermal differentiation. "GLI1 was found to be overexpressed in Ewing Sarcoma cell lines, regulated by EWS-FLI1 fusion protein independent of canonical Hh signaling pathway, as evidenced by lack of GLI1 response to exogenous SHH and cyclopamine treatment, and critical for Ewing Sarcoma proliferation." (PMID 36010600, 2022).
gallbladder carcinoma (2 papers, 2020 to 2025). "Nonetheless, aberrant SHH signaling is associated with various tumors, including gallbladder carcinoma; therefore, it is of great importance to maintain the local expression of SHH within the physiological intervals." (PMID 40003307, 2025). "However, the evidence for SHH in the microenvironment of gallbladder cancer is still required for the investigation." (PMID 31979397, 2020). "The expressions of SHH, PTCH, and GLI1 are upregulated in gallbladder cancer." (PMID 31979397, 2020).
gastric atrophy (2 papers, 2017 to 2023). "The severity of gastric atrophy may be influenced by the inhibition of the SHH signaling pathway by IL-1β, which may inhibit gastric-acid secretion and intracellular calcium release." (PMID 37687125, 2023).
glaucoma (2 papers, 2022 to 2026). Increased pressure in the eyeball due to obstruction of the outflow of aqueous humor. "Together, these findings establish NSUN4 as an m5C-dependent activator of the SHH pathway that protects retinal cells against excitotoxic injury, nominating it as a novel candidate for glaucoma neuroprotection." (PMID 41984922, 2026). "Currently, four of the five (80%) SHH variant carriers over the age of 40 have developed POAG, and we expect that more younger carriers will develop glaucoma as they age." (PMID 35749127, 2022). "SHH has not previously been associated with glaucoma, but the involvement of the pathway in the differentiation of PNC cells, which are important for anterior chamber development and subsequent ciliary body, Schlemm's canal, and iris formation, make it an obvious candidate." (PMID 35749127, 2022).
kidney tumors (2 papers, 2013 to 2022). "We analyzed the level of SHH mRNA by Q-RT-PCR in colon, lung, and kidney tumors as compared to normal adjacent tissues." (PMID 23940460, 2013). "These observed molecular differences between the brain and kidney tumors is further supported by their classification into different methylation subgroups (SHH and MYC, respectively), indicating that the tumors do not share a clonal origin." (PMID 35912263, 2022).
liver cirrhosis (2 papers, 2014 to 2018). "The findings presented here are also of relevance to liver cirrhosis, characterized by activation of stellate cells, in part by a non-canonical SHH/RHOA axis." (PMID 30148884, 2018). "Pharmacological inhibition of the SHH pathway results in an attenuation of fibrosis in a variety of in vivo models, namely unilateral ureteral obstruction (UUO), systemic sclerosis and liver cirrhosis, although others did not report improvements." (PMID 24622053, 2014).
liver disease (2 papers, 2019). "SHH was detected by immunohistochemistry (IHC) on paraffin-embedded liver sections in subjects (N = 69) with biopsy proven NAFLD and no liver disease (control)." (PMID 30744560, 2019).
mesothelioma (2 papers, 2013 to 2014). A usually malignant and aggressive neoplasm of the mesothelium which is often associated with exposure to asbestos. "Moreover, in situ hybridization analysis of mesothelioma tumors showed similar results that the expression of SHH and DHH was mostly associated with the tumor cells." (PMID 25422081, 2014). "SMO and SHH expression levels were analyzed in 46 mesothelioma tissue specimens with real-time RT-PCR, and correlation with survival was analyzed with univariate and multivariate Cox proportional hazards models, Kaplan-Meier survival curves, and the log-rank test." (PMID 23379358, 2013). "The Hedgehog pathway expression in mesothelioma tumors was recently analyzed using qRT-PCR, and SHH gene expression was only detected in tumor tissue but not in non-tumor pleural samples." (PMID 25422081, 2014).
myeloid malignancies (2 papers, 2014 to 2015). "Of these pathways, SHh signaling is gaining considerable attention as a therapeutic target for myeloid malignancies, despite the fact that its role in normal and malignant human hematopoiesis remains poorly defined and controversial." (PMID 24740159, 2014). "This study has provided the impetus for the on-going Phase 1b/ll combination SHH inhibitor and TKI inhibitor clinical trials for patients with advanced myeloid malignancies to both halt progression and prevent relapse." (PMID 25889765, 2015).
Non-alcoholic steatohepatitis (2 papers, 2019 to 2025). "Hepatic expression of Sonic Hedgehog (SHH) is associated with Non-alcoholic fatty liver disease (NAFLD) and development of Non-alcoholic steatohepatitis (NASH)." (PMID 30744560, 2019).
Obesity (2 papers, 2019 to 2025). Accumulation of substantial excess body fat. "For instance, obesity downregulates SHH signaling, including the expression of GLI1, GLI2, and GLI3." (PMID 31316554, 2019).
orofacial cleft (2 papers, 2023 to 2024). A disorder of facial skeleton that is characterized by cleft lip and/or cleft palate that result in feeding, speech and hearing problems caused by failures during development. "SHH has been associated with orofacial clefts in mice and human studies." (PMID 38227085, 2024). "The main aim of this specific study is to assess the presence of SHH, SOX3, WNT3A and WNT9B proteins by immunohistochemistry within the non-syndromic cleft-affected epithelium and connective tissue in non-syndromic orofacial cleft patient groups together with a comparison with the control group." (PMID 37366674, 2023). "However, whilst our results indicate no role for SHH and SOX3 in our study group, overall, we cannot exclude their involvement in orofacial cleft morphopathogenesis." (PMID 38227085, 2024).
osteoarthritis (2 papers, 2020 to 2021). A noninflammatory degenerative joint disease occurring chiefly in older persons, characterized by degeneration of the articular cartilage, hypertrophy of bone at the margins and changes in the synovial membrane. "SHH autocrine treatment of osteoarthritis MSC stimulates proliferation, chondrogenesis, hypertrophy, and replicative senescence with elevated SASP gene expression including IL1B, IL6, CXCL1, and CXCL8." (PMID 34646822, 2021). "In addition to this data, it is known that wogonin has been demonstrated in separate instances to have inhibitory activity on SHH and WNT signaling, processes which are upregulated in osteoarthritis and mediated by the primary cilium." (PMID 32132930, 2020). "It has been found that pathways controlled by the primary cilium in early development such as sonic hedgehog (SHH) and WNT signaling are dysregulated in osteoarthritis, alluding to a role of an as of yet uncharacterized failure of ciliary function in the development of osteoarthritis." (PMID 32132930, 2020).
pineoblastoma (2 papers, 2023 to 2025). Pineoblastoma is a rare, malignant type of supratentorial primitive neuroectodermal tumor (sPNET), found mainly in children (less than 10% of cases are reported in adults), and located in the pineal region of the brain but that can metastasize along the neuroaxis. "Pineoblastomas are described as having four molecular subgroups in the latest WHO classification and ATRTs have been divided into the tyrosinase (TYR), MYC, and SHH subgroups." (PMID 37835574, 2023).
pituitary tumor (2 papers, 2021 to 2023). A benign or malignant neoplasm affecting the pituitary gland. "Since ACTH-, GH- and PRL-immunopositive PitNETs show the highest SHH and GLI1 levels, we propose that HH signaling activity may play a role in formation and/or maintenance of these pituitary tumor subtypes as it is known for classical HH-associated tumors." (PMID 37476499, 2023).
polymicrogyria (2 papers, 2022 to 2023). A developmental brain abnormality characterized by an excessive amount of small convolutions on the surface of the brain and cognitive dysfunction. "It is unknown whether D/V patterning of the telencephalon is affected in JS; these patients often show cortical malformations, including polymicrogyria, that could be caused by overactive SHH signaling in outer RGCs." (PMID 35584663, 2022).
rheumatoid arthritis (2 papers, 2014 to 2022). A chronic, systemic autoimmune disorder characterized by inflammation in the synovial membranes and articular surfaces. "A sonic hedgehog (SHH)-Gli signaling pathway member GLI1 is involved in the pathogenesis of rheumatoid arthritis through synovial fibroblast proliferation." (PMID 36040971, 2022).
salivary gland tumors (2 papers, 2024 to 2025). "Other salivary gland tumors, such as pleomorphic adenoma, adenoid cystic carcinoma, and mucoepidermoid carcinoma, are characterized by strictly cytoplasmic and nuclear expression of SHH and GLI‐1, respectively." (PMID 40930949, 2025).
situs inversus (2 papers, 2014 to 2025). A congenital condition in which there is complete right-to-left reversal of the position of the major thoracic and abdominal organs (that is, they are arranged in a mirror image of the normal positioning). "Extrahepatic biliary atresia, most likely caused by abnormal morphogenesis of the extrahepatic bile duct, has also been discussed in animal models for situs inversus and abnormal SHH signaling and may be a potential cause of bile retention, and subsequently hepatic necrosis." (PMID 24743779, 2014).
soft tissue sarcoma (2 papers, 2021). A malignant neoplasm arising from muscle tissue, adipose tissue, blood vessels, fibrous tissue, or other supportive tissues excluding the bones. "Recently, SHH signaling activation was shown to induce undifferentiated soft tissue sarcomas in a mouse model." (PMID 33906647, 2021).
syndactyly (2 papers, 2019 to 2020). A disease characterized by the presence of syndactyly, including syndromic and non-syndromic forms. "Hence, loss-of-function mutations of RAB23, TWIST1, and GLI3 will be associated with a high SHH activity and syndactyly." (PMID 31637260, 2019). "In humans, gene mutations that lead to an increase in the activity of SHH will also lead to persistent GREM1 expression and syndactyly." (PMID 31637260, 2019).
Ureteral obstruction (2 papers, 2020 to 2024). Obstruction of the flow of urine through the ureter. "In unilateral ureteral obstruction (UUO) models, rhein reduces the expression of SHH, Gli1, and Snail, significantly improving renal interstitial fibrosis by regulating the SHH-Gli1-Snail signaling pathway." (PMID 39770507, 2024).
Viral infections (2 papers, 2010 to 2024). "Viral infections such as by influenza have been known to interfere with SHH signaling, disrupt epithelial junctions, and consequently increase epithelial exfoliation." (PMID 39597960, 2024).
Acheiropodia (1 paper, 2021). "We reasoned that the likely cause of the acheiropodia in this proband is altered SHH expression during limb development." (PMID 33863876, 2021). "Acheiropodia, congenital limb truncation, is associated with homozygous deletions in the LMBR1 gene around ZRS, an enhancer regulating SHH during limb development." (PMID 33863876, 2021). "Acheiropodia is associated with homozygous deletions in the LMBR1 gene around ZRS, an enhancer regulating SHH during limb development, but how these deletions lead to this phenotype is unknown." (PMID 33863876, 2021). "In summary, while we cannot conclusively rule out that alteration of the TAD boundary is responsible for this phenotype, our results strongly suggested that removal of these CTCF sites in humans alters the interaction between ZRS and the SHH promoter, likely leading to the acheiropodia phenotype." (PMID 33863876, 2021).
ACTHomas (1 paper, 2020). "SHH and its target gene GLI1 were also shown to be overexpressed in GHomas, ACTHomas, and prolactinomas, further supporting that excess SHH signaling is involved in the development/maintenance of hormone-producing PAs." (PMID 32153500, 2020).
acute promyelocytic leukemia (1 paper, 2015). An aggressive form of acute myeloid leukemia (AML), characterized by arrest of leukocyte differentiation at the promyelocyte stage, due to a specific chromosomal translocation t(15;17) in myeloid cells. "For example, SHH activates downstream transcription factor GLI-1 in several hematological malignancies, with prevalent expression observed in AML and acute promyelocytic leukemia (APL) patients." (PMID 26483188, 2015).
alcoholism (1 paper, 2023). "HPE has a heterogeneous etiology, potential causes include maternal diabetes, alcoholism, infections during pregnancy, drugs such as retinoic acid, chromosomal syndromes such as trisomy 13, and recessive autosomal mutations like SHH, SIX3, and ZIC2." (PMID 36845789, 2023).
anaplastic thyroid cancer (1 paper, 2018). "In anaplastic thyroid cancer, SHH pathway maintains the self-renewal property of CSCs30." (PMID 29540668, 2018).
Ataxia (1 paper, 2023). Ataxia refers to impaired coordination of voluntary muscle movement.
bacteremia (1 paper, 2018). "An interesting observation was that in contrast to the significant increase in the level of cell-associated SHH, the soluble SHH level in the bone marrow reduced markedly following E. coli bacteremia." (PMID 29535725, 2018). "Our current study revealed that E. coli bacteremia significantly upregulated SHH expression by bone marrow hematopoietic cells." (PMID 29535725, 2018). "Along with the increased expression of SHH in the bone marrow, expression of Gli1 by marrow cells was significantly upregulated at both mRNA and protein levels following bacteremia." (PMID 29535725, 2018). "In this study, we observed that SHH mRNA expression by nucleated BMCs was significantly upregulated during the early stage of E. coli bacteremia, indicating the involvement of transcriptional regulation in the enhancement of SHH expression." (PMID 29535725, 2018). "We, therefore, determined if ERK-SP1 signaling was involved in the regulation of SHH expression during the host response to bacteremia." (PMID 29535725, 2018). "Marrow lin− cells also exhibited a significant increase in SHH expression 48 h following initiation of bacteremia." (PMID 29535725, 2018). "At both 12 and 24 h of bacteremia, SHH mRNA expression by BMCs was significantly upregulated." (PMID 29535725, 2018). "Furthermore, marrow lin+, lin−, and lin-c-kit+ cells all exhibited a significant increase in SHH expression at 48 h of E. coli bacteremia." (PMID 29535725, 2018). "SHH protein level in bone marrow cell (BMC) lysates was markedly increased at both 24 and 48 h of bacteremia." (PMID 29535725, 2018).
benign ovarian tumor (1 paper, 2021). "Meanwhile, IHC scores of SHH and SQSTM1 were higher in borderline ovarian tumors and even higher than those in benign ovarian tumors." (PMID 34076346, 2021).
bile reflux (1 paper, 2021). "Although SHH-signaling is not active in normal adult esophageal cells, acid and bile reflux trigger abnormal activation of SHH-signaling in the esophagus, thereby contributing to BE pathogenesis." (PMID 33916875, 2021).